USP11 (ubiquitin specific peptidase 11)
Diseases named in the same sentence as USP11 in open-access papers (continued):
Sharing a sentence is not in itself a finding about the gene and the disease.
cancer (continued). "For example, when USP11 is overexpressed, it can not only transform normal cells into cancer cells but also inhibit cell necrosis and apoptosis by stabilizing x-linked inhibitor of apoptosis protein (XIAP), thereby promoting the occurrence of tumors." (PMID 35359344, 2022). "This will not only improve our comprehensive understanding of the biological behavior of USP11 but will bring light to the treatment of cancer patients." (PMID 35359344, 2022). "Inhibitors targeting USP11 should be designed in cancers promoted by USP11, and drugs that promote the expression of USP11 should be designed in cancers inhibited by USP11." (PMID 35359344, 2022). "In view of the dual role of USP11 in cancer, its dual effects need to be considered when designing drugs to target USP11." (PMID 35359344, 2022). "Recently, USP11 has rapidly emerged as an important cancer-related regulator, and these studies have shown that USP11 relies on its deubiquitinating enzyme catalytic activity to regulate the occurrence and progression of a variety of cancers." (PMID 35715413, 2022). "In this paper, we systematically summarize the role of USP11 in various cancer-related signaling pathways and focus on the targeting of USP11 as a potential therapeutic strategy for a variety of cancers." (PMID 35715413, 2022). "Recently, USP11 is also a member of the USPs family that is emerging as central to the regulation of various cancer progression." (PMID 35715413, 2022). "In this review, we summarize the role of USP11 in different cancers and discuss the advantages and possibilities of targeting USP11 as a new therapeutic strategy for a variety of cancers." (PMID 35715413, 2022). "In this article, we systematically review the emerging role of the deubiquitinase ubiquitin-specific peptidase 11 (USP11) in many cancer-related pathways." (PMID 35715413, 2022). "Due to the different expression abundances of tumor-related proteins that can interact with USP11 in different cancer types, USP11 exhibits different oncogenic or tumor-suppressive roles in different cancer types." (PMID 35359344, 2022). "For example, mitoxantrone is a small molecule inhibitor of USP11, which has been shown to be effective in cancer cells overexpressing USP1159." (PMID 34526504, 2021). "To further study the contribution of USP11 DUB activity to USP11-mediated tumor suppression, we used a human haploid cancer cell line, HAP1, in which the single allele of USP11 had been knocked out using CRISPR/Cas9 technology." (PMID 30733438, 2019). "The tumor-suppressive role of USP11 identified above prompted us to evaluate USP11 expression in cancer patients." (PMID 30733438, 2019). "Taken together, these results suggest that in a significant fraction of human malignant tumors, USP11 is downregulated, and a reduced USP11 expression can function as a mechanism of PTEN inactivation in the absence of PTEN genomic loss." (PMID 30733438, 2019). "Further, our analysis of cancer patients suggests that reduced USP11 expression can be a mechanism of PTEN inactivation (or reduced expression) in the absence of PTEN deletion." (PMID 30733438, 2019). "Consistent with an important regulatory role, USP11 is dysregulated in a number of cancers, including pancreatic cancer, glioma, ovarian, and breast cancers, as well as hematological malignancies." (PMID 30373771, 2019). "USP11 has been recognized as a novel anti-cancer target by preventing repair of double-strand breaks in cancer cells via synthetic lethality." (PMID 30373771, 2019). "Additionally, ERK1/2 can inhibit the phosphorylation of USP11 and thus downregulate the level of cytoplasmic p21, which can play an oncogenic and pro-cancer role in BC." (PMID 40083330, 2025). "Given that USP11 is functionally linked to TLR-mediated signaling through the stabilization of TRAF6, we explored whether TLR activation influences cancer progression in USP11-KO CRC cells." (PMID 41419456, 2025).
cancer (continued). "Considering tumor-infiltrating FOXP3+ Treg cells may promote the immune escape of cancer cells, our findings suggest that USP11 could serve as a potential therapeutic target for the treatment of tumors with FOXP3-induced immune evasion." (PMID 38806474, 2024). "As such, USP11 emerged as a promising biomarker in the context of cancer." (PMID 39617751, 2024). "Usp11 knockout mice present with normal hematopoietic system development, suggesting that USP11 inhibition might be a valid therapeutic target in cancer." (PMID 38007584, 2024). "It has been established that USP11 participates in cancer development." (PMID 38229475, 2024). "Further analysis of the Cancer Cell Line Encyclopedia (CCLE) database showed that both NOTCH1 and USP11 were found to be collectively highly expressed in T-ALL cell lines compared with cell lines from other cancer types, and their levels present with a positive correlation in the T-ALL group." (PMID 38007584, 2024). "USP11 is also involved in the occurrence and progression of other cancers." (PMID 35359344, 2022). "In addition, the expression levels of USP11 in different normal tissues are greatly different, and the expression levels in different cancers are also different, so the role of USP11 in tumors cannot be generalized." (PMID 35359344, 2022). "In addition to inhibiting cancer progression by stabilizing tumor suppressor proteins, USP11 can also inhibit the occurrence of tumors by stabilizing proteins involved in DNA repair." (PMID 35359344, 2022). "The dysregulation of USP11 is related to multiple diseases and pathological processes, the expression of USP11 in multiple cancer and para-cancer tissue are significantly different, which implied that USP11 might serve a potential cancer-related biomarker." (PMID 35715413, 2022). "In addition, USP11 can also deubiquitinate and stabilize Mgl-1 in a RanBPM-dependent manner, thereby inhibiting the proliferation of cancer cells." (PMID 35359344, 2022). "In addition to the critical role of USP11 in multiple cancers, it regulates the occurrence and status of different diseases." (PMID 35715413, 2022). "The biological function of USP11 should be implemented in specific cancer types." (PMID 35359344, 2022). "Interestingly, hypoxia also inhibits deubiquitylating enzyme ubiquitin-specific peptidase 11 (USP11) (Martín Mateos, 2019), depletion of which causes HRR deficiency in cancer cells." (PMID 33796526, 2021). "Likewise, USP11 malfunction has been found in many types of cancer and related in tumour development and progression." (PMID 33369124, 2021). "The dysregulation of USP11 had been found in a variety of human cancers." (PMID 33369124, 2021). "Notably, USP11 is downregulated in cancer patients, and correlates with PTEN expression and FOXO nuclear localization." (PMID 30733438, 2019). "The function of USP11 in different types of cancers is paradoxical." (PMID 31592114, 2019). "Given that drugs targeting chromatin-modifying enzymes are being explored as anticancer therapies, both alone and in combination with DNA-damaging treatments, defining the role of the USP11/NuRD complex in DDR functions will aid the effort in developing promising cancer therapeutics." (PMID 31504778, 2019). "USP11 was originally identified by Valle and colleagues and because of its role in a plethora of cellular processes, including DNA damage response, modulation of cellular senescence and intracellular signaling, USP11 is an interesting target for cancer therapy." (PMID 29293652, 2018). "Indeed, USP11 was noted to be phosphorylated by S6Kinase that increases its interaction with eIF4B and subsequently enhanced cancer-promoting gene translation." (PMID 29483509, 2018). "Like USP7, USP11 appears to have multiple cancer-associated roles, that could either promote or suppress oncogenesis and therefore a better understanding of the USP7-USP11 interaction is warranted." (PMID 30367141, 2018).
cancer (continued). "Finally, if small-molecule inhibitors of USP4, USP15, and/or USP11 are developed, it will be interesting to pursue their potential in cancer therapy." (PMID 26455393, 2015). "This was particularly exciting, as modulating USP11 itself may open new avenues of anti-cancer drug discovery." (PMID 22773947, 2012). "Finally, USP11 can also control the stability of ARID1A by competing with TRIM32 to determine whether it is cancer-promoting or cancer-suppressing." (PMID 35359344, 2022). "Moreover, the transcription factor nuclear factor (erythroid-derived 2)-like 2 (NRF2), which plays a crucial role in cancer progression, was deubiquitinated by USP11, and the depletion of USP11 contributes to the suppression of cell proliferation and the induction of ferroptosis." (PMID 36612069, 2022). "Interestingly, USP11 in different cancers exhibits distinct roles." (PMID 33369124, 2021). "From other cancers it is also reported that besides USP28, the deubiquitinases USP7, USP8, USP10 and USP11 interact with NICD and regulate NOTCH1 signaling." (PMID 40456839, 2025). "To better demonstrate the function of USP11 in regulating NOTCH1 signaling, we utilized biochemistry and molecular assays coupled with bioinformatic analysis of cancer datasets to reveal a novel positive feedback loop between NOTCH1 and USP11 in T-ALL." (PMID 38007584, 2024). "USP11 functions as a tumor suppressor by stabilizing VGLL4 in a YAP-dependent manner, which inhibits cancer cell growth, migration, and invasion." (PMID 38722330, 2024). "In a recent study, it was discovered that USP11 has the ability to enhance the stability of TGFβ receptor type 2 (TGFBR2) and initiate downstream TGFβ signaling in cancer cells." (PMID 39420007, 2024). "The ubiquitinase Trim32 can ubiquitinate ARID1A and further promote its degradation, while USP11 inhibits the ubiquitination of ARID1A and maintains its cancer-inhibiting effect." (PMID 35715413, 2022). "HAUSP/USP7, USP10, USP11, USP13, OTUD3, and Ataxin-3 have all been recently identified as PTEN DUBs that control PTEN activity in different cancer-specific contexts." (PMID 36385557, 2022). "Consistent with a previous report, our data revealed that by deleting USP11, it was possible to prevent HCC tumorigenesis, proliferation and chemoresistance and induce cancer cell apoptosis." (PMID 34114341, 2021). "Moreover, some studies have shown that USP11 can inhibit cell autophagy through the ERK/mTOR pathway, which promotes the proliferation and metastasis of cancer cells." (PMID 40083330, 2025). "Interestingly, this observation was harmonious with the data acquired from clinical CRC specimens, lending weight to the notion that USP11 expression was elevated in CRC, potentially facilitating the progression of the cancer." (PMID 39617751, 2024). "TGFBR2 is deubiquitinated by USP11 to maintain the TGF-β signal pathway and the glycosylation of TGFBR2 enhances the radio-resistance and BC cell stemness; therefore, maintaining a normal TGF-β pathway is essential for cancer cell control." (PMID 39525474, 2024). "So far, USP11 has not been reported as a marker for diagnosing cancer, but it has been reported as a prognostic marker for cancer patients." (PMID 35359344, 2022). "USP11 plays different roles in different types of cancer, not only promoting cancer but also inhibiting cancer." (PMID 35359344, 2022). "In summary, we employed a genetic screen and took advantage of a cellular adaptation model to define a ubiquitination-dependent mechanism for R-loop regulation by SETX, which is controlled by the opposing activities of USP11 and KEAP1 with broad applications for cancer and neurological disease." (PMID 34526504, 2021).
cancer (continued). "USP11 contains a potential nuclear localization signal (NLS) sequence at 445‐452 amino acids on the C‐terminus that mediates its translocation into the nucleus, which is deleted or inactivated in non‐cancer samples." (PMID 34114341, 2021). "DUBs are critical key players in diverse processes such as (i) spermatogenesis (e.g. USP2, USP8, USP9y, USP14, USP26, Uchl-1, Uchl-3 and CYLD), (ii) cancer biology (e.g. USP7, USP10 and USP11), and (iii) stemness and differentiation (e.g. USP7, USP9x, USP22, USP44 and Psmd14)." (PMID 28659380, 2017). "Finally, while 15 DUBs were found to be significantly dysregulated in only one type of cancer, 7 (UCHL1, USP9X, USP11, USP10, USP22, COPS5 and COPS6) displayed multiple alterations in two or more tumor types." (PMID 21283576, 2011). "Furthermore, USP11-inactive compounds 16 and 36 were tested on the two cancer cell lines, PEO4 and MDA-MB-231,as negative controls." (PMID 41427185, 2025). "Given the significance of USP10, USP11, USP13 and OTUD3 in PTEN stability, the development of a potent PTEN activation approach through manipulation of these DUBs may represent an attractive strategy for cancer prevention and treatment." (PMID 36385557, 2022). "Moreover, USP11 and KLF4 levels were found to be negatively correlated in HCC cells and to have the opposite prognostic trend regarding HCC in the clinical setting, which supports the essential role of USP11 in cancer development." (PMID 34114341, 2021). "Notably, in HAP1 cells knocked out for USP11, reintroduction of WT, but not catalytically inactive CS, USP11 resulted in a decreased cancer cell growth, invasion, and glucose and glutamine metabolism." (PMID 30733438, 2019). "Thus, in the absence of USP11, SPRTN is inactivated by increased auto-proteolysis, which may lead to inefficient SPRTN-mediated DPC repair, generating genomic instability leading to cancer and premature aging." (PMID 33567341, 2021).
tumor (49 papers, 2011 to 2025). "In individuals with neoplasia, USP11 expression is downregulated, which is associated with the expression level of PTEN and the location of FOXO within the nucleus." (PMID 38139829, 2023). "In the nucleus, USP11 causes the stabilization of nuclear p21 by reversing p21 polyubiquitination and acts as tumor suppressor by regulating cell cycle progression." (PMID 35414784, 2022). "First, we have identified the X-linked tumor-suppressor USP11 as an important physiological PTEN DUB that antagonizes the PI3K/AKT signaling pathway." (PMID 30733438, 2019). "Similarly, the Kaplan Meier analysis, using the log-rank test, demonstrated that a lower USP11 grade on immunohistochemical staining was associated with both clinical and biochemical tumor recurrence." (PMID 38139829, 2023). "However, the underlying mechanism that USP11 has contradictory effects on tumor development in different types of tumors remains obscure." (PMID 35414784, 2022). "We found that overexpression of VCP could rescue tumor growth inhibition caused by USP11 knockdown." (PMID 33758608, 2021). "Consistently, tumor weights were significantly higher in NSG mice engrafted with Ctrl HCT-15 cells than those with USP11-KO HCT-15 cells." (PMID 41419456, 2025). "Single-cell multi-omics can analyze DUB expression in tumor heterogeneity and identify predictive markers, such as USP11 activity, for precision medicine." (PMID 41219748, 2025). "These insights identify USP11 as a promising molecular target for CRC treatment and support the repurposing of mitoxantrone as an inhibitor of USP11-driven tumor growth." (PMID 41419456, 2025). "To assess USP11’s effect on in vitro tumor formation, we performed a three-dimensional (3D) tumor spheroid formation assay." (PMID 41419456, 2025). "In tumor cells, USP11 has been reported to inhibit tumor progression through a PTEN-dependent mechanism involving apoptosis." (PMID 39780069, 2025). "USP11 is recognized as a tumor promoter and plays a vital role in cell division by regulating microtubule nucleation and facilitating bipolar spindle formation through its deubiquitination activity." (PMID 41052634, 2025). "Functional experiments using USP11-knockout and USP11-overexpressing CRC cell lines (HCT-15 and HT-29) revealed that USP11 promotes tumor cell proliferation, migration, colony formation, and 3D spheroid growth." (PMID 41419456, 2025). "We carefully analyzed the positivity of USP11 and E-cadherin by H scores as well as their correlation in every tumor nodule/focus." (PMID 39270819, 2024). "High levels of USP11 correlate with poor prognosis as it enhances ERα signaling pathways, promoting tumor growth." (PMID 39678489, 2024). "a series of studies revealed significant disparities regarding USP11 expression between tumor tissues and adjacent tissues." (PMID 39617751, 2024). "To investigate the function of Usp11 in normal and tumor development in vivo, we generated Usp11 knock-out (Usp11−/−) mice in the BL/6 background (see details in “Materials and methods”)." (PMID 39270819, 2024). "Meanwhile, USP11/USP20-FOXP3 presents potential therapeutic target for inhibiting FOXP3-induced tumor immune evasion, as FOXP3 itself cannot be targeted due to its important role in autoimmunity." (PMID 38806474, 2024). "A non‐biased screen of 67 human deubiquitinases revealed that USP11 is the most decisive determinant that leads to tumour cell initiation and progression." (PMID 38229475, 2024). "Of 100 tumor nodules/foci analyzed, a significant positive relationship between USP11 and E-cadherin H-scores was detected." (PMID 39270819, 2024).